HIF1A (hypoxia inducible factor 1 subunit alpha)
Diseases named in the same sentence as HIF1A in open-access papers (continued):
Sharing a sentence is not in itself a finding about the gene and the disease.
cancer (continued). "Variant genotypes of HIF-1α rs11549465 and rs11549467 SNPs were both associated with a significantly increased cancer risk." (PMID 33154192, 2020). "These fibroblasts-induced changes are associated with a decrease in the Hif1α level, which correlates with an elevation in the Fbp expression in the cancer cells." (PMID 31947613, 2020). "HIF-1α expression in cancer cells has been linked to the reduced ability of CD8+ T cells to recognize malignancy and lower the ability of T cells to proliferate." (PMID 33015012, 2020). "Various studies reported that the increased expression of HIF-1α was associated with cancer risk and cancer prognosis." (PMID 32884936, 2020). "Since an increase in the levels of HIF-1α protein is a phenomenon seen in most cancers, it provides a molecular mechanism for cancer-associated overexpression of GLUT1." (PMID 31936350, 2020). "Hypoxia-inducible factor-1α (HIF-1α), defined as an oxygen-regulated protein, is in marked association with cancer biology." (PMID 33681184, 2020). "The reprogramming of lipid metabolism has emerged as a hallmark of cancer, yet the relevance of HIF-1α to this process remains elusive." (PMID 33128030, 2020). "The reduced glycolytic activity of cancer cells caused by PD-L1 blockade would subsequently induce an adaptive hypoxic response and stimulate the production of HIF-1α." (PMID 33193345, 2020). "Consistently, a number of clinical studies have also confirmed that HIF-1α overexpression has tight association with the poor prognosis to radiotherapy in various cancer types." (PMID 32403326, 2020). "VHL mutation is often observed in cancer, which results in an increase of the HIF-1α protein level and IGF-1R transcription level." (PMID 32260198, 2020). "Eventually, although non mutated in the vast majority of cancer patients, the Hypoxia Inducible Factor-1α (HIF-1α) represents a critical gene in several solid tumors." (PMID 32932943, 2020). "EMT also associates with a progressively more cancer stem cell-like phenotype, reported to involve interactions between HIF-1α, ZEB1 and the soluble sCD44 splice variant, implicating hypoxia-regulated alternative splicing in cancer stem cell promotion." (PMID 32536347, 2020). "HIF-1α that is responsible for the observed effects is a target of antitumor action of vitamin C. HIF-1-alfa regulates cancer cell metastasis that is the major cause of death for patients with breast cancer." (PMID 33182353, 2020). "HIF-1α stable long non-coding RNA (HISLA) in exosomes derived from cancer-associated macrophages stabilizes HIF-1α via proline hydroxylase domain 2 (PHD2) and HIF-1α." (PMID 32746850, 2020). "Overexpression of HIF-1α is associated with an aggressive phenotype and increased mortality in many cancers." (PMID 33050416, 2020). "Among the articles that explored the relationships between HIF-1α SNPs and cancer risk, 4 focused on 3 SNPs (rs11549465, rs11549467 and rs2057482), and 33 focused on 2 SNPs, and the remaining 17 focused on 1 SNP." (PMID 33154192, 2020). "In a range of common cancer types, HIF-1α was positively associated with the proliferation marker Ki67 (Mki67), and several studies report that HIF overexpression in cells can promote cell proliferation." (PMID 32571767, 2020). "This study provided new evidence showing that different SNPs in HIF-1α exhibit different effects on overall cancer risk." (PMID 33154192, 2020). "Hypoxia inducible factor-1 alpha (HIF-1α; encoded by HIF1A) is abundantly expressed in most human carcinomas and their metastases." (PMID 32033410, 2020). "Despites numbers of case-control studies working on this area, the actual relationship of HIF-1α gene generic variant rs11549465 C>T imposing on cancer susceptibility remains unveiled." (PMID 31762805, 2019).
cancer (continued). "Hypoxia is a key hallmark of cancers with high levels of HIF-1α widely found in those that produce large tumors where the center is hypoxic." (PMID 31611882, 2019). "HIF1α 1790G/A (rs11549467) gene polymorphism is one of the most important gene polymorphism for certain cancers, such as PCa, and RCC." (PMID 31419966, 2019). "Upregulation of HIF-1α is usually detected in cancer cells, which is caused by the hypoxic condition in the solid tumor as well as the activation of some oncogene." (PMID 31849679, 2019). "The roles of HIF-1α have been well documented in cancer progression and implicated in CRC metastasis." (PMID 31291975, 2019). "In a sense, this meta-analysis has succeeded in giving a clearer clue of the relationship between HIF-1α rs11549465 C>T polymorphism and cancer risk." (PMID 31762805, 2019). "The loss of TTP has been reported in several human cancers; this correlates with the elevation of HIF1α and poor prognosis." (PMID 30717305, 2019). "STAT-3 is able to induce expression of cysteine cathepsins, possibly in cooperation with another cancer-associated transcription factor, hypoxia-inducible factor-1-alpha, HIF-1α." (PMID 31555270, 2019). "Another pivotal microenvironmental factor driving cancer-associated inflammation is hypoxia, which is essential for granulocytes and monocytes/macrophages infiltration and activation in vivo in a HIF-1α-dependent manner." (PMID 31157165, 2019). "Curcumin suppressed cancer-associated fibroblasts- (CAFs-) induced prostate cancer cell epithelial-to-mesenchymal transition by inhibition of ROS-induced MAOA/mTOR/HIF1a signaling." (PMID 31308852, 2019). "The HIF1A gene has many SNPs, but we focused on rs2057482 for the following reasons: First, the relationship between rs2057482 and cancer risk has been reported in previous epidemiology studies." (PMID 31744467, 2019). "In clinical studies, expression of HIF-1α has been suggested as a marker of a highly aggressive disease associated with poor prognosis and treatment failure in numerous cancers." (PMID 30754624, 2019). "HIF-1α is associated with the increased chemoresistant phenotype of cancer cells, and downregulated HIF-1α can increase the sensitivity toward etoposide treatment." (PMID 31711497, 2019). "The activation of HIF1α promotes the expression of several genes, including protein-encoding genes and ncRNAs, and facilitates stem cell renewal, cancer cell survival, metabolism and chemoresistance." (PMID 31514389, 2019). "HIF-1α expression is associated with GLUT-1 expression in many cancers, and both markers are associated with the poor prognosis of many cancers." (PMID 31105886, 2019). "Quercetin promotes loss of cell viability, apoptosis and autophagy in cancer by reducing β-catenin and HIF-1α stabilization, inducing caspase-3 activation and inhibiting of Akt, mTOR, and ERK phosphorylation." (PMID 31261749, 2019). "In a word, our finding has come to a fruition that HIF-1α rs11549465 C>T polymorphism was significantly related to an increase in cancer risk." (PMID 31762805, 2019). "Most of the genes encoding glycolytic enzymes and transporters are targets of HIF-1α in normal and cancer cells, except for those coding for hexose-phosphate isomerase (HPI) and monocarboxylate transporters (MCT) (GPI and SLC16 or SLC5 genes, respectively)." (PMID 31600993, 2019). "TET1 was shown to be a transcriptional co-activator associated with HIF-1α enhancement regulation in several human cancer cell lines from kidney, lung, liver and head and neck." (PMID 31739546, 2019). "They obtained a similar result that the HIF-1α rs11549465 C>T polymorphism predispose to higher overall cancer risk." (PMID 31762805, 2019). "In prostate cancer cells, uptake of lactate by MCT1 is enhanced by the cooperation of cancer-associated fibroblasts and the activation of HIF-1α, which promotes cancer progression." (PMID 31027222, 2019).
cancer (continued). "HIF-1α is associated with high incidence of cancer, poor prognosis, and resistance to chemotherapy or radiotherapy in cancer patients." (PMID 30832444, 2019). "Herein, we performed this more comprehensive meta-analysis on selected case-control studies in the aim of giving a more thorough demonstration of the association of HIF-1α rs11549465 C>T polymorphism with cancer risk." (PMID 31762805, 2019). "In the current meta-analysis, we systematically evaluate the relationship between HIF-1α rs11549465 C>T polymorphism and cancer risk by using 49 case-control studies." (PMID 31762805, 2019). "The results revealed that HIF-1α rs11549465 C>T polymorphism contributes to increased overall cancer risk." (PMID 31762805, 2019). "HIF-1A (for HIF-1α) genetic polymorphisms are associated with diseases for which the response to oxygen deprivation plays a central pathogenic role, i.e., cancer and cardiovascular diseases." (PMID 31214621, 2019). "Elevated expression of HIF-1α is associated with poor outcomes in multiple human cancers such as those of head and neck, breast and colorectal cancers." (PMID 30925729, 2019). "Our meta-analysis suggests that the rs205782 polymorphism of the HIF1A gene significantly decreases the overall cancer risk, based on the synthesis results of the included studies." (PMID 31744467, 2019). "We have recently identified SF3B1 on chromosome 2 as a Copy-number alterations Yielding Cancer Liabilities Owing to Partial losS (CYCLOPS) gene with a highly significant positive correlation to hypoxia-inducible factor-1α (HIF1α)." (PMID 31623347, 2019). "As part of it, HIF‐1 is considered to cause hyperexpression in the hypoxic region of cancer, but the HIF‐1α control glycolysis system increases metabolite flux to PPP." (PMID 30801869, 2019). "Similar to the failing myocardium, HIF1α is also induced in cancer cells and is associated with an increase in the expression of glucose transporters, glycolytic enzymes and PDK (resulting in suppressed mitochondrial GO)." (PMID 29951485, 2018). "HIF pathway (HIF-1α or HIF-2α activity) has been revealed to be associated with promotion of cancer cell stemness, where blocking HIF-1α or HIF-2α activity has been strongly contributed to self-renewal and proliferation capacities." (PMID 30349420, 2018). "HIF-1α is responsible for multiple effects that have been associated with enhanced cancer progression and poorer patient outcome." (PMID 29098360, 2018). "HIF-1α deregulation has been deeply implicated in different aspects of cancer biology, such as angiogenesis, cell resistance, and tumor invasion." (PMID 30234010, 2018). "EF24 exerts its anti-cancer activity by inhibiting cancer cell proliferation or causing apoptosis via multiple pathways, such as inhibiting NF-κB, inhibiting HIF-1α activity, and regulating reactive oxygen species (ROS)." (PMID 30619754, 2018). "Anti-angiogenic effects of sustained sorafenib therapy caused intratumor hypoxia, which induced HIF-1α and protected cancer cells from sorafenib treatment." (PMID 30619754, 2018). "Since HIF-1α and GLUT-1 are closely associated with cancer metastasis, we next sought to determine and compare the expression of HIF-1α and GLUT-1 in LoVo and HT29 cells." (PMID 30546057, 2018). "Increased adipose HIF-1α protein was detected with obesity-associated factors, which enhanced cancer progression." (PMID 30154386, 2018). "As HIF-1α overexpression is one of the main causes for the aggressiveness of cancer cells that is achieved after anti-angiogenic therapies, we investigated the effects of the treatments on intracellular HIF-1α production via western blot analysis." (PMID 30138430, 2018). "Activated CMA is also linked to HIF-1A degradation in cancer cells, which compromises the ability of cancer cells to respond to and survive hypoxia, suggesting the complex pathophysiological effect of CMA under hypoxic conditions." (PMID 29445095, 2018).
cancer (continued). "Another important role of EF24 is to regulate HIF-1α expression which is closely associated with the outcome of chemotherapy in cancer treatment." (PMID 30619754, 2018). "One consequence of HIF-1α activation is the upregulation of miR-210, which is associated with cancer progression and poor prognosis." (PMID 29596470, 2018). "HIF-1α expression and proangiogenic factor levels are correlated with an increased risk of mortality in several types of carcinoma." (PMID 29568362, 2018). "HIF-1α is overexpressed and its overexpression is associated with increased patient mortality in different human cancers." (PMID 29383199, 2017). "While dysregulated HIF1α and pAkt are associated with most forms of cancer, mutations in VHL are found predominately in ccRCC." (PMID 29053101, 2017). "The induced inhibition of HIF-1α expression was associated not only with a decrease in cancer cell's growth but also with an improvement in cancer-induced hepatic gluconeogenesis and skeletal-muscle wasting." (PMID 29152137, 2017). "Last, many molecules associated with general cancer mechanisms were regulated including bcatenin, HIF1α, MYC or aurora kinase A." (PMID 29299138, 2017). "In particular, these two oncometabolites have been associated with the aberrant stabilization of HIF-1a, a key protein in cancer that is commonly overexpressed in PCa cells." (PMID 28804274, 2017). "A high amount of adipocytes enhances cancer progression due to the increased expression of HIF-1α which causes the loss of ER α protein as stated in four articles." (PMID 28993797, 2017). "Hypoxia-inducible factor 1α (HIF-1α) is a transcription factor that is activated in response to oxygen deficiency, and HIF-1α expression is activated in several cancers under the intratumoral hypoxic stress that arises during pathogenic processes." (PMID 28489881, 2017). "The authors conjugated SWCNTs to siRNA to target the expression of hypoxia-inducible factor 1 alpha (HIF-1α), which is found in many human cancers and is associated with resistance to cancer therapy." (PMID 30970690, 2017). "Activation of HIF-1α is physiological during embryogenesis and in wound-healing processes, whereas in cancer, HIF-1α is associated with malignancy and poor prognosis." (PMID 29230384, 2017). "Overexpression of HIF-1α has been observed in many cancer types and associated with a poor prognosis." (PMID 28781970, 2017). "The association between mitochondrial respiration damage and HIF-1α inactivation despite hypoxia has also been observed in Rho zero cells and diverse cancer cell types, in which OXPHOS complexes I, III, IV, or V were pharmacologically inhibited." (PMID 29230384, 2017). "For instance, the expression and distribution of HIF-1α were found to be associated with human cancer progression in bladder, brain, kidney, breast, ovary, pancreas and prostate." (PMID 29228687, 2017). "Detailed immunohistochemistry research has indicated that dysregulation and overexpression of HIF-1α are heavily implicated in cancer biology, specifically in areas of vascularization and angiogenesis." (PMID 28974006, 2017). "A high amount of adipocytes enhances cancer progression due to the increased expression of HIF-1α which causes the loss of ERα protein." (PMID 28993797, 2017). "Cultured cancer-associated fibroblasts (CAFs) derived from primary PDAC exhibited a high basal level of hypoxia inducible factor 1a (HIF1α) that was both required and sufficient to modulate the expression of MCT4." (PMID 27623078, 2016). "To further assess the potential relationship between erythrocytosis, cancer outcome and HIF-1α deregulation, we characterized twelve PHD2 mutations found in polycythemic patients through a bioinformatics approach." (PMID 26754054, 2016). "Collectively, our data demonstrate that docetaxel-induced PHD1 phosphorylation increases the degradation of HIF-1α and causes cancer cell death in hypoxic conditions." (PMID 27263528, 2016).
cancer (continued). "HIF-1α is a subunit of a key transcription factor responsible for cellular response to hypoxia and implicated on many levels in cancer pathogenesis and biology." (PMID 27975057, 2016). "CDCA and DCA destabilised HIF-1α in all cells and significantly suppressed key cancer progression associated phenotypes; clonogenic growth, invasion and migration in DU-145 cells." (PMID 27416726, 2016). "We searched for HIF-1α mutations occurring in various human cancers, to identify a potential link between HIF-1α methylation and cancer progression." (PMID 26757928, 2016). "Hif-1α expression has been associated with the chemo-resistance of cancer cells by inhibiting apoptosis and induction of drug efflux." (PMID 26894974, 2016). "HIF-1α has been identified as a major regulator of adaptation to hypoxia and implicated in the malignant progression of cancers." (PMID 26869355, 2016). "Here, we investigated the molecular mechanism underlying docetaxel-induced HIF-1α degradation and cancer cell death under hypoxic conditions." (PMID 27263528, 2016). "The top disease and biological function networks identified from the siRNA screen that affected HIF-1α–NanoLuc activity include post-transcriptional modification, post-translational modification, protein degradation, and cancer associated networks." (PMID 26882567, 2016). "Here we show a previously undescribed function for NQO1 in stabilizing HIF-1α, a master transcription factor of oxygen homeostasis that has been implicated in the survival, proliferation and malignant progression of cancers." (PMID 27966538, 2016). "In the present study, we found that HIF1α expression in cancer cells was positively associated with the expression of Tenascin-C in cancer cells, and this finding suggests that hypoxia promotes Tenascin-C expression in ESCC cells." (PMID 26731558, 2016). "The histological appearance of the stromal cells with high HIF-1α protein expression, including irregular branched cytoplasm, suggested these to be cancer associated fibroblasts (CAFs)." (PMID 27634881, 2016). "TRX increases the expression and activity of HIF-1α which is associated with poorer prognosis and metastatic potential in certain cancers." (PMID 26824423, 2016). "It is clear that mitochondrial defect in cancer cells can cause a shift in energy metabolism, in which hypoxia-inducible factor-1α (HIF-1α) plays an important role as an activator of aerobic glycolysis and lactate production." (PMID 26918353, 2016). "The TME-associated HIF-1α-mediated hypoxia pathway also regulates cancer EMT through Notch signaling." (PMID 26989421, 2016). "A remarkable frequency of common genetic alterations that are associated with HIF-1α expression occurs in cancer patients." (PMID 26757928, 2016). "Dr. Dang and coworkers have made great efforts to establish the associations among HIF-1α, Warburg effect, and glycolysis in human cancers." (PMID 27231905, 2016). "Hypoxia or overexpression of HIF-1α is associated with resistance to cancer chemotherapy and increased patient mortality." (PMID 26856989, 2016). "In some cancers, accumulation of HIF-1α can result from loss-of-function mutations in proteins that cause HIF-1α degradation, such as the Von Hippel-Lindau tumor suppressor (pVHL) or the enzymes that produce cofactors for the prolyl hydroxylases (PHDs)." (PMID 27058900, 2016). "Consistent with the role of HIF1α in epithelial to mesenchymal transition (EMT) of cancer cells, LPA stimulates EMT and associated invasive cell migration along with an increase in the expression levels N-cadherin and Slug/Snail2." (PMID 27166196, 2016). "Hypoxia is a hallmark of many human cancers, a consequence of cancer cell proliferation consuming oxygen and aberrant blood vessel development, leading to the local induction of the transcription factors HIF1α and HIF2α." (PMID 25605240, 2015).